WT1 (WT1 transcription factor)
Diseases named in the same sentence as WT1 in open-access papers (continued):
Sharing a sentence is not in itself a finding about the gene and the disease.
tumor (continued). "To conclude, our findings revealed the tumour promoting potential of WT1 in NSCLC cells by facilitating cell proliferation, survival, invasion and tumorigenesis." (PMID 37667197, 2023). "WT1-targeted immunotherapy has been considered a promising therapeutic strategy for various cancers owing to its tumor-specific expression and high immunogenicity." (PMID 36672344, 2023). "Immunohistochemistry showed that the tumor cells were positive for CK, Claudin4 and mesothelial markers, such as WT-1, Calretinin, D2-40, and CK5/6." (PMID 37194050, 2023). "Wilms' tumor 1 (WT1) dendritic cell vaccine therapy (WT1-DC) is an immuno-cell therapy that has been implemented against various cancers as a tumor-specific immunotherapy targeting the common cancer antigen WT1." (PMID 38143707, 2023). "WT1 is a transcription factor that is unique among transcription factors because it functions as both a tumor suppressor and an embryonic development regulator." (PMID 36968605, 2023). "As expected, the enhanced cytotoxicity of WT1 TED2 split against WT1-HLA-A*02:01+ tumor cell lines, was followed by elevated T cell activation by WT1 TED2 split." (PMID 38022650, 2023). "We have previously shown that exercise mobilized T-cells and γδ T-cells proliferate better ex vivo in response to tumor antigen (e.g. WT1, PRAME) peptide loaded dendritic cells and phosphate antigens, respectively." (PMID 37077913, 2023). "To reiterate, WT1 is the topmost tumor antigen as per the NCI pilot project ranking of tumor antigens." (PMID 36992219, 2023). "In our analysis, WT1 expression levels were high in tumor tissues relative to autologous renal tissue." (PMID 36818371, 2022). "One of the +1 labeled positive cases actually had only two WT1-positive tumor cells (nuclear staining), with weak and moderate stain intensity, respectively." (PMID 35453662, 2022). "The middle region of HNRNPU is bound by RNA polymerase II, colocalizes with Wilms’ tumor (WT1), and modulates WT1 transcription." (PMID 36012592, 2022). "The normal renal tissue adjacent to the tumor constantly manifested for all of the evaluated cases, nuclear WT1 staining of podocytes and, also, of the epithelial cells, constituting the parietal layer of Bowman’s capsule." (PMID 35453662, 2022). "Although it has been believed to act as an oncogene, WT1 has also been reported to be considered as a tumor suppressor in AML." (PMID 36500358, 2022). "WT1 is a zinc finger transcription factor that acts as both a tumor suppressor and an oncogene, depending on different cancers, so it is also called a chameleon gene." (PMID 35915803, 2022). "Although WT1 overexpression is a characteristic feature in most AML, it was argued that WT1 was an oncogene or a tumor suppressor." (PMID 36500358, 2022). "In normal human hematopoietic cells, WT1 appears to be a tumor-suppressor gene; indeed, its overexpression induces growth arrest, reduces colony formation, and promotes spontaneous differentiation." (PMID 35743376, 2022). "Altogether, these results demonstrate that knocking down the WT1 gene significantly suppressed tumor progression and the development of BRAFV600E PTC." (PMID 35123502, 2022). "The TAA/ABL1 mRNA ratios in the tumor cell line-spiked samples were highly reproducible, with a CV of 0.05 and 0.11 for WT1/ABL1, 0.1 and 0.21 for PRAME/ABL1, and 0.12 and 0.21 for BIRC5/ABL1." (PMID 36248870, 2022). "Although this finding represents a limitation of the current study, it illustrates the paradoxical role of WT1 as a tumor suppressor and potential oncogene depending on its expression level and/or the cellular context and will be the subject of future study." (PMID 35406427, 2022). "It has been reported that WT1 functions as both an oncogene and tumor suppressor in multiple malignancies, playing a critical role in cell survival, proliferation and differentiation." (PMID 35123502, 2022).
tumor (continued). "WT1 is a universal tumor target antigen due to its expression pattern in multiple different cancer entities, thus having great potential for developing immunotherapies." (PMID 34821951, 2022). "WT-1 is Wilms’ tumor-1, an oncoprotein that is highly expressed in GBM and is considered a tumor-associated antigen." (PMID 35690784, 2022). "Then, we analyzed the effect of the WT1 expression level on the proliferation, migration and tumor growth of BRAFV600E PTC cells." (PMID 35123502, 2022). "The high expression of WT1 can upregulate E‐cadherin expression and induce tumor cell epithelial‐mesenchymal hybrid transition (EMHT)." (PMID 35373928, 2022). "Genes associated with proliferation, and cell survival (BCL2L1), and tumor- cell growth (WT1) pathways for development of cancer were overexpressed, whereas molecules relevant to differentiation resistance (CSF1R) were underexpressed." (PMID 35246110, 2022). "The Wilms’ tumor gene, WT1, is transcriptionally regulated by HIF and is known to play a crucial role in tumorigenesis and invasiveness of certain types of cancers." (PMID 35465313, 2022). "WT1 was initially identified as a tumor-suppressor gene involved in the pathogenesis of childhood renal Wilms’ tumor." (PMID 35743376, 2022). "Tumor tissues expressed significantly higher levels of WT1, HIF-1α, B-FGF, and c-MYC and significantly lower levels of SLC22A18 relative to autologous renal tissue." (PMID 36818371, 2022). "Cytochemical immunoreactivity of RCC cryosections showed ample WT1 protein levels within undifferentiated tumor areas comprising epithelial components." (PMID 35453662, 2022). "We found that WT1 overexpression induces G2/M checkpoint arrest through the upregulation of IL-24, thereby inhibiting tumor cell proliferation." (PMID 35915803, 2022). "We first analyzed the expression profile of WT1 using the TIMER (Tumor Immune Estimation Resource) database." (PMID 35915803, 2022). "The human Wilms tumor 1 (WT1) gene is a tumor suppressor gene that spans ∼50 kb and consists of 10 exons." (PMID 35308512, 2022). "WT1 is also highly immunogenic, as both peptide immunization and DNA-based immunization were shown to be effective in inducing WT1-specific cytotoxic T lymphocytes (CTLs) capable of more easily identifying and destroying WT1 positive tumor cells." (PMID 35453662, 2022). "In this study, mice with the Wt1-CreER genotype showed that ~50% of tumor stromal cells undergo Wt1-Cre-mediated recombination." (PMID 36233262, 2022). "Ultimately, by targeting the tumor-associated antigen Wilms’ tumor-1 (WT1), the tumor-antigen specificity was assessed by demonstrating a superior antigen-specific T cell stimulating capacity of PD-L-silenced IL-15 DCs." (PMID 35250967, 2022). "Emerging WT1-targeted RCC immunotherapy will require adequate case selection and sustained efforts to standardize the quantification of tumor-associated antigens for aRCC and its many subtypes." (PMID 35453662, 2022). "Mice with endothelial-cell-specific Wt1 knockout using Tie2-CreER or VE-cadherin-CreER have reduced vascular density and tumor volume in melanoma and lung cancer." (PMID 36233262, 2022). "In contrast, protein expression of CD146 and WT1, markers of the intestinal lamina propria, was preserved in regions adjacent to intraepithelial tumor cells." (PMID 34798385, 2021). "Tumor-associated antigens that have been tested in single-target GBM vaccines include survivin and WT1." (PMID 34041034, 2021).
tumor (continued). "This first discovery of WT1 as the responsible gene in an autosomal-recessive condition classified it as a tumor-suppressor gene." (PMID 34299295, 2021). "ESK1, an ImmTAC recognizing intracellular Wilms’ tumor 1 (WT1) antigen presented in HLA-A*02:01, was able to lyse WT1-positive tumor cells in vitro and reduce tumor outgrowth of AML, ALL and mesothelioma tumors in NSG mice." (PMID 33466732, 2021). "In a few patients, mutations in other genes, such as WT1 and IDH2, were also found in the corresponding CP samples with lower tumour cell fractions (TCFs) calculated by variant allele frequencies (VAFs) than those found in the BC samples." (PMID 33990592, 2021). "This translocation, which results in active fusion protein involving the Ewing sarcoma (EWS) and Wilms tumor (WT1) genes, is pathognomonic." (PMID 34635162, 2021). "This syndrome is caused by large chromosomal deletions in chromosome 11p13, including PAX6 and the Wilms tumor gene (WT1), this genotype represents 10% of all classical aniridia cases." (PMID 34065151, 2021). "Similar responses were seen in mice immunized with an endogenous tumor antigen [Wilms’ tumor 1 (WT1) gene product]." (PMID 34055652, 2021). "To investigate the reason behind the better outcomes of the lower quartile WT1 group and the favorable 6-gene signature group, we evaluated the differences in tumor microenvironments between groups based on the TCGA’s BC primary tissue RNA-seq dataset." (PMID 33987034, 2021). "Tumor shrunk after the treatment and became undetectable on day 26 in 4 of the 15 WT1 peptide vaccine-treated mice and 9 of the 15 anti-PD-1 antibody-treated mice." (PMID 34355173, 2021). "Nonetheless, results showed that the combination of HAGE- and WT1-ImmunoBody® was able to significantly delay tumour growth and prolong mouse survival when compared to mice in the control group." (PMID 34262856, 2021). "One is the Wilms’ tumor suppressor protein (WT1), a master transcription factor for kidney development and homeostasis and a dual actor displaying a tumor suppressor and oncogenic role in normal and malignant hematopoiesis." (PMID 33917766, 2021). "Apart from its sensitivity in identifying DFSP, WT1 is very helpful in distinguishing recurrent/residual tumor cells from fibroblasts/myofibroblasts of scar tissue after surgical excision, which can share CD34 immunostaining with the cells of DFSP." (PMID 33445443, 2021). "More importantly, the combined HAGE/WT1 ImmunoBody® vaccine significantly delayed tumour growth in the B16/HHDII+/DR1+/HAGE+/WT1+ tumour model and prolonged mouse survival in the prophylactic setting in comparison to non-immunised control mice." (PMID 34262856, 2021). "The number of TIIs per one unit of tumor-emitting bioluminescence was statistically significantly higher in WT1 peptide vaccine-treated mice than anti-PD-1 antibody-treated and control mice." (PMID 34355173, 2021). "Data mining the immune epitope database with the T1-116C binding consensus and validation of peptide recognition using the T2 stabilization assay identified additional tumor antigens targeted by T1-116C, including WT1, gp100, Tyrosinase and NY-ESO-1." (PMID 33836029, 2021). "Further, we identified for the first time Wilms Tumor 1 gene (WT1), which is an oncogene in PCa26,27, as a new direct target of miR-642a-5p in PCa, providing novel insight into the role of miR-642a-5p as a tumor suppressor in PCa." (PMID 34504167, 2021). "WT1 was initially discovered as a tumor suppressor in WT and the first gene found to be inactivated in WT." (PMID 34722128, 2021). "Using the WT1 RNA expression profiles of the four types of BC primary tumor tissue downloaded from TCGA, we analyzed the correlation between WT1 expression and the methylated sites." (PMID 33987034, 2021). "In terms of IHC features, tumor cells were generally positive for WT-1 C-terminal, while only 2 patients were focally positive for WT1 N-terminal." (PMID 34193155, 2021).
tumor (continued). "Positive expression of CR, CK5/6, WT1, and D2-40 were denoted in primary epithelioid tumor tissue, and PDX1 expressed the same pattern." (PMID 34789172, 2021). "Immunohistochemically, this tumor tested positive for vimentin, CD 99, glypican-3, synaptopysin, WT-1, CK, and EMA." (PMID 34054966, 2021). "In practice, WT1+/HLA-A*02:01+ primary tumor cells or cell lines were distinguished and lysed by WT1-CAR T cell." (PMID 34412685, 2021). "Wilms’ tumor 1 (WT1), a tumor-suppressor gene, can interact with lymphoid enhancer-binding factor 1 (LEF1) to mediate Wnt signaling activation." (PMID 34926267, 2021). "On the other hand, tumor shrunk after the treatment and became undetectable on day 26 in all mice treated with the combination therapy of WT1 peptide vaccine and anti-PD-1 antibody, and all but one mice survived for more than 66 days." (PMID 34355173, 2021). "In contrast, intense expression for WT-1 by the nuclei of malignant cells was detected in hens with fimbrial tumor and hens with tumors metastasized to distant organs (late stage OVCA)." (PMID 34314463, 2021). "Another peptide-based vaccine being investigated in the treatment of GBM utilized the Wilm’s tumor (WT1) gene." (PMID 34572775, 2021). "Tumor cells exhibited diffuse strong staining for cytokeratins (CKs), Vimentin, D2–40, Wilms’ tumor 1 (WT-1) and INI-1." (PMID 33761726, 2021). "WT1 can promote tumor cell proliferation, inhibition of apoptosis, and interacts with cytoskeletal proteins to promote migration, invasion and angiogenesis." (PMID 34257533, 2021). "It has different functions, including developmental, tumor suppressor and oncogenic properties, due to the production of various isoforms of WT1 resulting from an alternative splicing." (PMID 34943491, 2021). "The overall goal of this study was to evaluate the capacity of a combined HAGE/WT1 sequence-based vaccine to eliminate/prevent the growth of HAGE/WT1 expressing tumours." (PMID 34262856, 2021). "One study suggested that mouse visceral, but not subcutaneous, white adipose tissue arises from cells expressing Wilms tumor (Wt1) gene." (PMID 34708046, 2021). "Of considerable interest was the absence of immunoreactivity, both cytoplasmic and nuclear, for WT1 in all the other neoplasms with which DFSP can be confused." (PMID 33445443, 2021). "Wilm’s tumor (WT1) protein is overexpressed in hematologic tumor and various solid tumors and it is recognized as one of the most promising targets for cancer immunotherapy." (PMID 33937323, 2021). "Similar results for MCT4 were obtained also in a multivariate analysis which included age, gender, tumor histological subtype, previous cancer diagnosis, type of therapy (surgery, radio- or chemotherapy), and mesothelial marker staining (WT1 and calretinin)." (PMID 32887638, 2020). "This study contained both very slow and very fast progressive tumors, and also includes cases in which WT1 vaccine therapy succeeded in suppressing tumor progression but FDG PET-CT was performed because tumor progressed thereafter." (PMID 32991475, 2020). "These WT1 mutation analyses demonstrate that all cell lines had only mutant WT1 genes and that they are bona fide tumor cells." (PMID 33379206, 2020). "The WT-1 gene was originally identified as a tumor suppressor gene and is overexpressed in a variety of neoplasms." (PMID 33080944, 2020). "BASP1 is a direct target of miR-191 and BASP1 inhibition by miR-191 leads to transactivation of WT1, which activates the Wnt pathway to promote tumor progression." (PMID 33247706, 2020). "WT1 is a zinc finger transcription factor located on 11p13, which was first identified as a tumor suppressor gene." (PMID 32736539, 2020). "We showed a differential response in functional avidity of WT1-specific TCR-engineered T cells against different peptide-pulsed model APC tumor lines." (PMID 31972992, 2020).
tumor (continued). "Studies have indicated that WT1 can facilitate tumor progression as an oncogene through modulating tumor cell proliferation, apoptosis, and metastasis." (PMID 33426068, 2020). "Number of infiltrated CD8T cells observed in right WT1+ tumor was larger than that in left WT1− tumor." (PMID 32259478, 2020). "Tumours in mice transplanted with PANC‐1‐sh‐WT1#1 were significantly smaller than those in mice transplanted with PANC‐1‐sh‐NC." (PMID 31845546, 2020). "Since the 1990s, monocyte-derived DCs loaded with tumor-specific peptides such as Wilms tumor 1 (WT1) have been utilized in clinical studies and trials as vaccines against a variety of cancers." (PMID 33374342, 2020). "The positive correlation between WT1 score and Ki67 labelling index implies its relation to tumor grade." (PMID 32856872, 2020). "This study was followed up by a phase I/II trial (MESODEC) in which treatment-naïve patients received WT1-targeting DC-therapy during chemotherapy, followed by pleurectomy/decortication (P/D) in the case of a resectable tumor (NCT02649829)." (PMID 32582537, 2020). "Analysis of the CTNNB1-pathways and WT1-pathways suggested that they are differentially regulated across these tumor regions." (PMID 32843649, 2020). "While the ascites-derived OV3291 cell line does not express WT1 in Western blot, its matched tumor-derived cell line TOV3291G, as well as its tumor of origin, does express the WT1 protein." (PMID 32784519, 2020). "Increased WT1 score significantly associated higher Bcl2 and Ki67 labelling indices, increasing WHO tumor grade and tumor’s histopathologic type (p<0.05) showing staining pattern variability by tumor entity and cell type." (PMID 32856872, 2020). "Tumoral cells are usually reactive for immunohistochemical antibodies anti-calretinin, Wilms tumor 1 (WT-1), and cytocheratins; sarcomatoid phenotype can be highlighted with anti-vimentin staining." (PMID 33419364, 2020). "Targeting WT1 is a promising therapeutic strategy in solid tumors and hematological malignancies because WT1 is necessary for tumor growth and leukemogenesis." (PMID 32580769, 2020). "DSP-7888 is a peptide cancer vaccine that includes WT1 derived peptides: it has shown to induce both a CD8+ and CD4+ mediated immune response against WT1 overexpressing tumor cells." (PMID 32850962, 2020). "Immunohistochemistry of the original and xenografted tumor revealed positivity for WT1, MIB1 (arrows: nuclear staining), Annexin IV." (PMID 33143664, 2020). "EWSR1 is also known to be translocated in 13 other tumour types with at least 17 other fusion partners, common partners being, WT1, ATF1, CREB1, YY1, NFATC2, and others." (PMID 33488267, 2020). "The patients had previously treated inoperable or postoperatively relapsed NSCLC and received activated DCs pulsed with either autologous tumor lysates or peptide antigens (WT1, MUC1, CEA) matched to their HLA-A type." (PMID 33679709, 2020). "Cancer-testis antigens or tumor-associated self-antigens such as melanoma antigen-1 (MAGE-1), WT1, NY-ESO-1, and synovial sarcoma X (SSX) are not only expressed in tumor cells but also partly in normal tissues such as embryonic or germ cells." (PMID 32964055, 2020). "The tumor is believed to be dependent on the continued activity of the oncogenic EWS-WT1 transcription factor." (PMID 32345977, 2020). "Targeting WT1 is a promising therapeutic strategy in various solid cancer because WT1 is an oncoprotein necessary for tumour growth and metastasis." (PMID 31845546, 2020). "Here, we provide a versatile model to evaluate HLA-A2-restricted WT1 epitope-specific responses by TCR-engineered T cells based on the combination of a tumor cell-based APC with a rapid engineering method such as mRNA electroporation." (PMID 31972992, 2020). "We used WT1 as a tumor-specific target as it is overexpressed in the majority (>80-90%) of patients with AML, including cell-cycle quiescent AML stem cells located in the BM." (PMID 33101274, 2020).